VEGFC (vascular endothelial growth factor C)
Diseases named in the same sentence as VEGFC in open-access papers (continued):
Sharing a sentence is not in itself a finding about the gene and the disease.
tumor (continued). "In tumor samples, the expression of IDH2, HIF1b, HIF2a, EGRF, PTEN and STAT3 was significantly downregulated, but HIF1a and VEGFC expressions were upregulated in U87MG STAT3 KO variant in comparison with U87MG cells." (PMID 38654280, 2024). "In our study, we demonstrated that the lipid raft protein STOML2 upregulates VEGFC expression to promote tumor angiogenesis, leading to the increased sensitivity to bevacizumab." (PMID 38214751, 2024). "Correspondingly, the occurrence of lymphogenic metastasis correlates with lymphatic vessel density within and around the tumor tissue, expression of lymphangiogenic factors such as vascular endothelial growth factor C (VEGF-C), and with lymphatic invasion." (PMID 39682225, 2024). "In one study, exogenous histidine administration resulted in a decrease in the expression of tumor markers associated with glycolysis (GLUT1 and HK2), inflammation (STAT3), angiogenesis (VEGFB and VEGFC), and stem cells (CD133)." (PMID 37760495, 2023). "The loss of DUSP2 in pancreatic ductal adenocarcinoma (PDAC) promotes the processing of VEGFC, which is subsequently transported by EVs to the tumor microenvironment (TME), leading to lymphangiogenesis." (PMID 36831512, 2023). "The VEGFR3 signaling pathway in tumor-associated macrophages (TAMs) is activated by the abundant VEGFC in CRC, resulting in the induction of CRC immune escape and acceleration of tumor growth." (PMID 37120534, 2023). "Representatively, tumor expression of vascular endothelial growth factor C promotes deletional tolerance and dysfunction of tumor-specific CD8+ T cells." (PMID 37130873, 2023). "The expression of vascular endothelial growth factor receptor 2 (VEGFR2) and vascular endothelial growth factor C (VEGF‐C) in the tumor specimens was analyzed using immunohistochemistry." (PMID 37605832, 2023). "A relevant feature was the overexpression of factors such as VEGFA, VEGFC and Ang2, which are not only pro-angiogenic, but also support the growth of tumor cells." (PMID 36874116, 2023). "We also observed that tumor and endothelial cells released vascular endothelial growth factors, including VEGFC and VEGFA, as well as platelet-derived growth factors, including PDGFA and PDGFC." (PMID 37333982, 2023). "VEGFC, for example, can enhance radiotherapy efficacy and anti-tumor immunity in gliomas when combined with VEGFR2." (PMID 37790751, 2023). "Our main results suggest that the high expression of VEGFC is closely related to tumor progression and perineural invasion." (PMID 38203550, 2023). "Our main results suggest that VEGFC gene expression is closely related to tumor progression, DFS, and the presence of perineural invasion." (PMID 38203550, 2023). "In immune subtypes analysis, VEGFC was highly expressed in C3 (inflammatory) and C6 (transforming growth factor β dominant) across various cancers, indicating its potential role as a tumor promotor." (PMID 37852616, 2023). "VEGFC and VEGFD are usually expressed in primary human tumors or their related matrix and are secreted by tumor cells, immune cells and tumor-associated fibroblasts, while VEGFR3 is mainly expressed in LECs." (PMID 37803421, 2023). "According to the study, tumor-derived vascular endothelial growth factor-C (VEGF-C) stimulated LECs to produce chemokines, which in turn helped MDSCs find their way to lymph nodes." (PMID 37056346, 2023). "It has been reported that VEGFC is the most representative and important factor promoting the formation of tumor lymphangiogenesis." (PMID 37124061, 2023). "The increased CCL2 is secreted into the tumor microenvironment, promoting the recruitment of tumor associated macrophages (TAM), and then promoting lymphatic metastasis through the secretion of vascular endothelial growth factor C (VEGF-C)." (PMID 37907984, 2023). "Overexpression of the vascular endothelial growth factor C (VEGFC) gene was found in patients with tumor progression (p = 0.022) and in patients with perineural invasion (p = 0.030)." (PMID 38203550, 2023).
tumor (continued). "The presence of an increased VEGFC gene expression in CSCC tumor samples with perineural invasion is remarkable compared to those without perineural invasion (0.89 ± 0.29 vs. 0.37 ± 0.07; p = 0.030)." (PMID 38203550, 2023). "VEGFC expression exhibited positive correlations with immune infiltration scores, suggesting low tumor purity." (PMID 37852616, 2023). "As a key step of tumor lymphatic metastasis, lymphangiogenesis is regulated by VEGFC‐VEGFR3 signaling pathway mediated by immune cells, mainly macrophages, in the tumor microenvironment." (PMID 36670069, 2023). "The expression of VEGFC in hepatocellular carcinoma is positively correlated with tumor size and number but negatively correlated with disease remission rate and disease-free survival time." (PMID 37762426, 2023). "An increased expression of protein VEGFC in samples with tumor progression supported these results (p = 0.050)." (PMID 38203550, 2023). "Meningeal lymphatic angiogenesis facilitated by increased expression of VEGFC promotes lymphatic drainage, tumor antigen presentation, and immune surveillance." (PMID 36831512, 2023). "Interdicting the VEGFC/VEGFR-3 axis has been widely reported to reduce the rate of lymphatic metastasis in a number of tumor-bearing experimental invivo models 60-62." (PMID 37416763, 2023). "SCC metastatic cells disseminate to tumor-draining-lymph nodes through intratumoral lymph vessels (LVs), spurred by the lymphangiogenic vascular endothelial growth factor C (VEGF-C)." (PMID 37686421, 2023). "Numerous experiments have demonstrated that tumour-secreted VEGFC is a key cytokine involved in tumour development and the immune response." (PMID 35600335, 2022). "As expected, ITGA5, PLAU, PLAUR, SERPINE1, TGFB1, and VEGFC were consistently overexpressed in tumor tissues compared to normal tissues (log2FC > |1| and p ≤ 0.01)." (PMID 36425786, 2022). "In fact, tumor cells are able to directly modulate LV function, by secreting the pro-lymphangiogenic vascular endothelial growth factor C (VEGF-C), promoting intratumoral lymphatic growth, dilating LV and impairing lymphatic pumping." (PMID 35663931, 2022). "In this study, we identified the role of the transcription factor zinc finger with KRAB and SCAN domains 5 (ZKSCAN5) in interacting with histone methyltransferase SETD7 and mediating VEGFC transcription and tumour lymphangiogenesis." (PMID 35600335, 2022). "Periostin expression has been reported to correlate with vascular endothelial growth factor-C (VEGF-C) expression in both the tumor and serum of HNC patients." (PMID 36224629, 2022). "VEGFC accumulated in the tumor context induces tumor lymphatic vessels to release chemokines such as CCL19 and CCL21 that can attract tumor cells through their binding to CCR7." (PMID 36612017, 2022). "It is possible that the over-expression of COX-2 stimulated vascular endothelial growth factor-C upregulation and consequently promoted lymphangiogenesis which was the first step for tumor cells spreading to the regional lymph nodes." (PMID 36425143, 2022). "Vascular endothelial growth factor-C (VEGFC) is one of the most crucial lymphangiogenic growth factors, which can stimulate the formation of tumor lymphatics." (PMID 36203528, 2022). "Initially quiescent, tumor lymphatic vessels become lymphangiogenic in response to the expression of pro-lymphangiogenic factors, such as VEGFC produced by tumor and tumor stromal cells." (PMID 36612017, 2022). "In this study, we identified three immune-related genes, VEGFC, VCAN, and TNFSF, overexpressed in tumor tissues of high-risk patients and PDXY and APOLD1 upregulated in the low-risk group." (PMID 35382776, 2022). "Through tumour-derived VEGFC and macrophage-derived COX-2, chronic stress restructured lymphatic networks within and around tumours, providing pathways for tumour cell escape." (PMID 35454788, 2022).
tumor (continued). "VEGFC is the main regulator of angiogenesis and accelerates tumor progression by promoting angiogenesis by binding to the kinase insert domain receptor (VEGFR-2)." (PMID 35587748, 2022). "It is reported that VEGFC can also regulate the immune system, making it easier for tumour cells to escape immune surveillance." (PMID 35600335, 2022). "Treatment with VEGFA and VEGFC inhibitors decreased tumor metastasis into LNs and lungs in a mouse mammary-gland cancer model." (PMID 35626729, 2022). "VEGFR3 blockade reduces metastatic spread and lymphangiogenesis in a number of tumor models, as the VEGFC : VEGFR3 signaling pathway is one of the quintessential drivers of LEC proliferation and lymphatic expansion." (PMID 35372032, 2022). "Recent evidence suggests that VEGFC is also an immunomodulator that modulates the immune system, making tumor cells more likely to evade immune surveillance." (PMID 36203528, 2022). "The results of this study showed that LINC00467 was significantly elevated in CRC, and LINC00467 played a tumor-promoting role in CRC by regulating miR-128-3p/VEGFC." (PMID 35587748, 2022). "Other leukocyte-derived inflammatory cytokines, such as IL1β, TNFα or IL10, attract VEGFC-secreting leukocytes that amplify tumor lymphangiogenic activity." (PMID 36612017, 2022). "The vascular endothelial growth factor-C (VEGF-C) secreted from malignant tumor cells is the major regulator in tumor-induced lymphangiogenesis to promote LN metastasis." (PMID 35265612, 2022). "Emerging evidence shows that various aspects of tumour development can be promoted through the autocrine regulation of VEGFC." (PMID 35600335, 2022). "In advanced ccRCC, when tumor cells have disseminated throughout the organism, the VEGFC-induced lymphatic network further enhances the dissemination of tumor cells to healthy tissues." (PMID 34067671, 2021). "Detecting vascular endothelial growth factor C (VEGF-C), a kind of tumor biomarker, is of significant clinical importance in evaluating the prognosis of patients with cancer." (PMID 33500522, 2021). "Vascular endothelial growth factor C (VEGFC) is active in blood vessels and lymphatics endothelial cell proliferation and migration, therefore contributing to tumor metastases." (PMID 35126454, 2021). "A large number of studies have confirmed that the expression levels of VEGFC and VEGFD in many types of tumor cells are correlated with tumor-associated lymphangiogenesis, tumor cell invasion into lymphatic vessels, and LNM." (PMID 34552874, 2021). "VEGFC-dependent lymphatic vessels promote the access of tumor antigens to lymph nodes, thereby enhancing the anti-tumor immune system of low-grade tumors." (PMID 34067671, 2021). "VEGFC-dependent lymphangiogenesis is one of the main routes of metastatic dissemination for tumor cells." (PMID 34067671, 2021). "Here, we showed that treatments targeting the VEGFC signaling pathway inhibit the proliferation of endothelial cells, but also slow down tumor cell proliferation, cells that aberrantly express VEGF receptors/co-receptors." (PMID 34067671, 2021). "In a tumour context, the lymphangiogenic growth factors VEGFC and VEGFD are produced by a variety of cell types including tumour cells, stromal cells, tumour-infiltrating macrophages and activated platelets." (PMID 33572413, 2021). "This transient effect is in part explained by the development of an alternative lymphatic network dependent on the production of VEGFC by tumor cells or cells of the microenvironment in reaction to the stress induced by the drug." (PMID 33461580, 2021). "Cancer-associated fibroblasts (CAFs) express and secret CCBE1, thereby contributing to VEGFC maturation and tumor lymphangiogenesis in CRC." (PMID 32089745, 2020). "The next bone-related protein is vascular endothelial growth factor C (VEGFC) belonging to crucial factors in embryonal and tumor angiogenesis processes, as well as involved in vascularization during bone formation." (PMID 33287223, 2020).
tumor (continued). "VEGFC is one of the key factors promoting malignant cell spread, as demonstrated both in mouse tumor models and during human cancer progression." (PMID 32132179, 2020). "Secretion of VEGFC, expression of its receptors on tumor cells and the resulting autocrine/paracrine effect of this cytokine, are major determinants of MB tumor size." (PMID 33067561, 2020). "For example, numerous works on xenogeneic tumor transplantation models in mice have demonstrated that targeting the VEGFC-VEGFR3 and VEGFD-VEGFR3 axis can inhibit tumor lymphangiogenesis, lymphadenopathy, and lymph node metastasis." (PMID 33013360, 2020). "Collectively, these results highlight BACH as a novel regulator of blood and lymphatic vessel formation during both embryonic development and mouse tumor expansion, placing it upstream of VEGFC in these cascades." (PMID 32132179, 2020). "Accumulating evidence suggest that the up and downstream effectors of the VEGFC-VEFGR3/Flt4 axis form a complicated biochemical network which work in synergy to facilitate tumor lymphangiogenesis and lymphatic metastasis." (PMID 32752094, 2020). "These bevacizumab-adapted cells secrete more VEGFA, VEGFB, VEGFC, and PlGF, which induce migration of tumor cells and angiogenesis of endothelial cells in this medium in comparison with the parental cells." (PMID 32560565, 2020). "We conclude that, unexpectedly, lymphangiogenesis genes, especially VEGFC, negatively regulate MB tumor cell aggressiveness." (PMID 33067561, 2020). "In xenograft or transgenic tumor models, stimulation of lymphangiogenesis by VEGFC promotes malignant cell dissemination." (PMID 32132179, 2020). "Chitin downregulated vascular endothelial growth factor C (VEGF-C) synthesis that was related to tumor angiogenesis." (PMID 33339290, 2020). "In conclusion, unexpectedly, the common thread between the different MB subgroups is the downregulation of tumor cell aggressiveness by VEGFC." (PMID 33067561, 2020). "In two different models of MB, high amounts of VEGFC/VEGFC receptors correlate with lower tumor size and lower migration of tumor cells." (PMID 33067561, 2020). "The results presented here demonstrate that members of the BACH family regulate VEGFC expression, thereby promoting angiogenesis and lymphangiogenesis during zebrafish development and in ovarian and lung mouse tumor models." (PMID 32132179, 2020). "VEGFC can, thus, be added to a growing list of tumor and metastatic proteins, including CXCR4 and MMP1, all of which are transcriptionally regulated by BACH1." (PMID 32132179, 2020). "The pressure of selection mediated by the treatment, stimulated VEGFC expression by human tumor cells." (PMID 31938054, 2020). "For instance, lymphatic factors (like VEGF-A and VEGFC) can bring about tumor metastasis and spread in mouse cancer models." (PMID 33013360, 2020). "Cells expressing high levels of VEGFC also form smaller tumors when subcutaneously injected into the flank of nude mice, thus highlighting a negative regulatory role for VEGFC on tumor growth." (PMID 33067561, 2020). "Rapamycin inhibits the expression of VEGFC and significantly suppresses tumor-related lymphangiogenesis and lymph node metastasis in mammals." (PMID 32936824, 2020). "VEGFC is a potent regulator of the growth and maintenance of blood and lymphatic vessels during embryonic development, tumor expansion, and metastasis." (PMID 32132179, 2020). "Using the NSCLC tumour model, we found that Afatinib suppressed the expression of LYVE-1, VEGFR2, 3, VEGFC, and VEGF in tumour tissues, indicating reduced lymphatic formation and possible VEGFC/VEGFR3 pathway involvement in the process." (PMID 31892990, 2020). "Nonetheless, the profound abrogation of tumor growth caused by the VEGF receptors blockage, and consequent inhibition of VEGFC function, suggests the VEGFC pathway has an important role in the aggressive phenotype of 4C11+ cells." (PMID 31069961, 2019).
tumor (continued). "Expression of miR526b and miR655 in human tumour tissue was significantly correlated with lymphangiogenesis markers VEGFC, VEGFD, and LYVE-1." (PMID 31277414, 2019). "The VEGFR3 signaling is stimulated by its main cognate ligand, vascular endothelial growth factor C (VEGF-C), which in turn promotes tumor progression." (PMID 30901976, 2019). "This is presumably due to the inhibition of VEGFC signaling—the only VEGF ligand expressed in these cells—which leads to an impaired tumor development." (PMID 31069961, 2019). "Specific signaling pathways, such as vascular endothelial growth factor C (VEGF-C) and its cognate receptor VEGF receptor 3 (VEGFR-3) are confirmed to stimulate tumor-associated lymphangiogenesis, as well as lymph node metastasis in experimental tumor models." (PMID 30849953, 2019). "In summary, we found that the VEGFC pathway is highly correlated with tumor aggressiveness in our murine model." (PMID 31069961, 2019). "The proliferation and migration of lymphatic endothelial cells (LECs) in tumor microenvironment were driven by the VEGFC/VEGFR3 axis." (PMID 30131072, 2018). "In vivo studies showed that SRC-1 knockdown restricted tumor growth, reduced the numbers of LYVE-1-positive lymphatic vessels, and decreased the levels of VEGFC in tumor tissues." (PMID 29717026, 2018). "Vascular endothelial growth factor-c mRNA and protein expression is increased in tumor tissues, blood and urine samples of BC patients." (PMID 30544619, 2018). "Recent findings demonstrate that the bioactive lipid lysophosphatidic acid (LPA) promotes PCa progression by regulating vascular endothelial growth factor-C (VEGF-C), a critical mediator of tumor lymphangiogenesis and lymphatic metastasis." (PMID 30384405, 2018). "Tumor-derived lymphangiogenic growth factors (especially Vascular Endothelial Growth Factor-C (VEGFC)) can drive the formation of lymphatic vessels, providing an interface for lymphatic vessel invasion and distant metastasis." (PMID 29692812, 2018). "On the other hand, tumour cells can express and secrete several lymphangiogenic factors, including VEGFC/D, to promote the formation of new lymphatic vessels in the tumour stroma." (PMID 30189837, 2018). "It is well known that increased levels of vascular endothelial growth factor-C (VEGF-C) promote active tumor lymphangiogenesis and lymphatic tumor spread to regional lymph nodes." (PMID 28771226, 2017). "We found a concentration-dependent increase in tumour cell VEGFC expression and protein secretion, suggesting the COX2-PGE2 inflammatory pathway as a plausible mediator of stress-induced lymphatic remodelling." (PMID 26925549, 2016). "IL-6 has been shown to promote tumor lymphangiogenesis through vascular endothelial growth factor-C (VEGF-C) induction in tumor cells." (PMID 27383632, 2016). "Knockdown of VEGFC blocked stress-induced LYVE-1+ LVD in primary tumours, demonstrating a key role for tumour cell VEGFC in stress-induced lymphatic remodelling." (PMID 26925549, 2016). "To investigate the contribution of tumour cell-derived VEGFC in SNS-induced lymphatic remodelling, we used short hairpin RNA to stably silence VEGFC in MDA-MB-231 tumour cells." (PMID 26925549, 2016). "Blocking macrophage recruitment prevented stress-induced VEGFC expression in tumours and blocked lymphatic dissemination as shown by reduced lymph node metastasis." (PMID 26925549, 2016). "Many preclinical datasets have indicated that the blockade of the VEGFC/VEGFR-3 pathway inhibits tumor spread to lymph nodes and beyond." (PMID 27145366, 2016). "We show that VEGFC derived from tumour cells is required for stress to induce lymphatic remodelling and that this depends on COX2 inflammatory signalling from macrophages." (PMID 26925549, 2016). "The changes in lymphatic vessels can be detected even in early tumor initiation; for instance, the expression of vascular endothelial growth factor C (VEGF-C), a key promoter of lymphangiogenesis, is enhanced at this stage." (PMID 27203207, 2016).